RNU6-577P (RNA, U6 small nuclear 577, pseudogene)
Gene: Small nuclear RNA gene on chromosome 2 (36,867,398 to 36,867,495, reverse strand). Ensembl gene ENSG00000252756.
Homologues: Orthologues: chimpanzee U6 (96% identical), macaque U6 (94% identical), dog U6 (72% identical), mouse Gm55959 (60% identical). Paralogues in human: RNU6-20P (85% identical), RNU6-271P (85% identical), RNU6-737P (85% identical), RNU6-128P (84% identical), RNU6-1316P (84% identical), RNU6-214P (84% identical), RNU6-738P (84% identical), RNU6-80P (84% identical), RNU6-1104P (83% identical), RNU6-1124P (83% identical), RNU6-1145P (83% identical), RNU6-12P (83% identical), and 1285 more.